BATF2 (basic leucine zipper ATF-like transcription factor 2)
Diseases named in the same sentence as BATF2 in open-access papers (continued):
Sharing a sentence is not in itself a finding about the gene and the disease.
schistosomiasis (1 paper, 2019). An infectious disease caused by parasitic trematodes of the genus Schistosoma that colonize human blood vessels and release eggs that can cause granulomatous reactions leading to acute (swimmer's itch or acute schistosomiasis syndrome) or chronic disease. "In fact, Batf2 deficiency rendered animals more susceptible to acute schistosomiasis associated with a rapid wasting disease that was not confounded by a differential body weight in animals from both groups." (PMID 30542107, 2019). "Intriguingly, however, Batf2 deficiency aggravated small intestinal fibrogranulomatous responses during acute murine schistosomiasis." (PMID 30542107, 2019). "In contrast, Batf2 was important to limit untoward immune responses and small intestinal fibro-granulomatous inflammation during murine schistosomiasis." (PMID 30542107, 2019). "Altogether, these findings demonstrate that Batf2 is required by the host to control T helper mediated inflammatory responses in the small intestine during acute schistosomiasis." (PMID 30542107, 2019). "Batf2 deficiency did not prompt any major aggravation of the liver pathology as determined by the measure of hepatomegaly during acute schistosomiasis." (PMID 30542107, 2019). "In striking contrast, Type 2-controlled schistosomiasis exacerbates during infected Batf2−/− mice with increased intestinal fibro-granulomatous inflammation, pro-fibrotic immune cells, and elevated cytokine production leading to wasting disease and early death." (PMID 30542107, 2019). "Altogether, our findings therefore strongly argue against a therapeutic target for the BATF2 blockade in the context of Type-2 controlled schistosomiasis in agreement with its recently reported anti-inflammatory role against pathological tissue Th17 responses during T. cruzi infection." (PMID 30542107, 2019). "Consistent with the previously reported higher expression rate of Batf2 by CD8+ T cells when compared to CD4+ T cells, our present data reveal a more pronounced inflammatory surge in CD8+ cells within the T cells compartment of Batf2-deficient mice during acute schistosomiasis." (PMID 30542107, 2019). "This suggests a reduced ability of small intestinal macrophages, undergoing classical macrophage M1 activation during schistosomiasis in the absence of Batf2." (PMID 30542107, 2019).
soft tissue sarcoma (1 paper, 2024). A malignant neoplasm arising from muscle tissue, adipose tissue, blood vessels, fibrous tissue, or other supportive tissues excluding the bones. "We first explored the expression levels of BATF2 in human soft tissue sarcoma." (PMID 38420020, 2024).
tumor (30 papers, 2012 to 2025). "Because of the myriad of tumor suppressor functions of BATF2, it is imperative to elucidate the mechanisms underlying how BATF2 is regulated during tumorigenesis and development." (PMID 38420020, 2024). "A previous study showed that BATF2 has an antitumor effect through the upregulation of IL-12p40, a component of the bioactive cytokine IL-12, in tumor-associated macrophages." (PMID 36635421, 2023). "The protein coded by BATF2 was shown to have an antitumor effect in a mouse model through upregulation of IL-12 p40 in tumor-associated macrophages, leading to CD8+ T-cell activation and tumor accumulation." (PMID 36077244, 2022). "The BATF2 gene encoding the BATF2 protein is a newly discovered tumor-suppressor gene isolated using subtractive hybridization." (PMID 34778372, 2021). "The basic leucine zipper ATF-like transcription factor 2 (BATF2) has been implicated in inflammatory responses and anti-tumour effects." (PMID 33452462, 2021). "The decreased BATF2 IHC expression was associated with sex, tumor size, histological grade and TNM stage." (PMID 32650804, 2020). "In addition, in tumor-associated macrophages, the expression of IL-12p40 was facilitated through the interactions between BATF2 and the p65/p50 heterodimer, which induces the antitumor adaptive immune responses of CD8+ T cells." (PMID 36635421, 2023). "To our surprise, we found that the expression of BATF2 is higher in primary tumor compared with normal tissue; whether there is loss of function of BATF2 in those patients’ tumor needs further investigation." (PMID 37777155, 2023). "BATF2 blocks tumor progression through multiple mechanisms, such as the inhibition of epithelial–mesenchymal transition (EMT), CCN1 transcription, c-Jun expression, and angiogenesis." (PMID 39678510, 2024). "Recently, we and others have identified basic leucine zipper transcription factor ATF-like 2 (BATF2) as a tumor suppressor." (PMID 38420020, 2024). "In vitro experiments involving cell cultures, tumor cell spheroids, and organoids were conducted to assess BATF2's impact on 5-Fu sensitivity and its interaction with drug transporters and signaling pathways." (PMID 39629124, 2024). "As a tumor suppressor gene, BATF2 plays a pivotal role in the prevention of tumor development and progression, although the specifics of its mechanism are yet to be fully elucidated." (PMID 39629124, 2024). "Accumulating studies, including ours, have demonstrated that basic leucine zipper transcription factor ATF (activating transcription factor)‐like 2 (BATF2) is a capable tumour suppressor that localises in the nucleus." (PMID 37151195, 2023). "Similar to in vitro data, we found that BATF2-KD tumor-bearing mice had upregulated expression levels of PD-L1, ZEB2, and p-AKT–PI3K." (PMID 37777155, 2023). "As a conclusion, BATF2 expression in tumor is positively correlated with antitumor immune cell infiltration." (PMID 37777155, 2023). "Basic leucine zipper (bZIP) transcription factor ATF‐like 2 (BATF2), also known as suppressor of activator protein 1 (AP‐1) regulated by interferon (SARI), was identified as a tumour suppressor, as well as a type I interferon‐inducible gene." (PMID 37151195, 2023). "To further demonstrate the tumour suppressive effect of BATF2 in CRC, we performed knockdown tests by using siRNAs against BATF2 (siBATF2)." (PMID 37151195, 2023). "BATF2 has been previously reported as a novel tumor suppressor gene that inhibits the growth of cancer cells through repression of hepatocyte growth factor receptor/MET signaling." (PMID 37777155, 2023). "The expression of BATF2 from circulating tumor cells and tissues can be serve as an efficient biomarker to predict diagnosis, prognosis, and immunotherapy efficacy." (PMID 37777155, 2023).
tumor (continued). "Is it possible through metabolism reprograming or affecting cell proliferation or tumor immune landscape especially macrophages that has been reported and has decent amount of BATF2 expression in basal level ?" (PMID 37777155, 2023). "Emerging studies, including ours, have suggested that BATF2 is a tumour suppressor, suppressing the growth and metastasis of multiple tumours mainly through binding to AP‐1, thereby regulating the expressions of the downstream genes." (PMID 37151195, 2023). "These regions contained tumor-related genes, such as Muc16, Pik3, and Bcl2 in amplification regions and Hras, Notch1, Apc2, Ccnd1, Batf2, Dapk3, Smarca4, Traf2, Traf3, Cdk3, and Cdh4 in deletion regions." (PMID 36424557, 2022). "Many studies have shown that METTL3 promotes tumor growth and aggressiveness by regulating the mRNA decay and stability or mRNA translation of numerous tumor-associated genes, such as SOCS2, BATF2, EGFR, TAZ, MAPKAPK2, and DNMT3A." (PMID 35456475, 2022). "Recent studies have reported that BATF2 overexpression inhibits tumour cell proliferation and metastasis, and promotes apoptosis in various cancer types." (PMID 33452462, 2021). "A potential immunotherapy combination comprising a DNA methyltransferase inhibitor and BATF2 exerts an anti-tumour effect on medulloblastoma." (PMID 33452462, 2021). "ELISA results indicated that injected BATF2-EVs led to significant decrease in SDF-1α levels in tumour tissues." (PMID 33452462, 2021). "We found that HIF-1α expression was activated during U251 tumour progression between d7 and d21 and was decreased in the BATF2 group at all three different stages." (PMID 33452462, 2021). "Taken together, BATF2 inhibits tumour growth and MDSCs recruitment most likely through a decrease of the SDF-1α/CXCR4 signalling." (PMID 33452462, 2021). "By calculating the percentages of bone marrow-derived cell (CD45+, mainly including MDSCs and macrophages) recruitment into tumour, we found that upregulation of BATF2 significantly inhibited CD45+ cell infiltration (p < 0.001)." (PMID 33452462, 2021). "These mentioned studies imply that BATF2 can be used as a prognostic indicator of patients, a monitoring sensor for tumor therapy, and a potential target in gene therapy." (PMID 34565331, 2021). "In contrast, MRI scanning and H&E staining of U87-sh-BATF2 downregulation xenografts showed that tumour masses were significantly increased when BATF2 was downregulated (red dotted lines highlight tumour areas)." (PMID 33452462, 2021). "The results showed that localisation of SDF-1α surrounding tumour cells was attenuated by BATF2 overexpression." (PMID 33452462, 2021). "Five weeks after tumour implantation, we found that overexpression of BATF2 in U251 cells significantly inhibited tumour growth (red dotted lines highlight the tumour regions)." (PMID 33452462, 2021). "Collectively, these data confirmed that BATF2 inhibits tumour growth in both intracranial and subcutaneous GBM models." (PMID 33452462, 2021). "We found that calculating BATF2+ EV numbers in tumour tissues can distinguish stages I–II and III–IV GBM patients from healthy donors (I–II GBM vs. healthy donors: p < 0.01; III–IV GBM vs. healthy donors: p < 0.001)." (PMID 33452462, 2021). "We identified that BATF2 acts as a tumor suppressor in GC by inhibiting cell proliferation, migration, and invasion." (PMID 32650804, 2020). "In tumor-associated Mφs, the expression of Il12b was facilitated through interactions between BATF2 and the p65/p50 heterodimer, leading to the induction of anti-tumor adaptive immune responses." (PMID 30753547, 2019).
tumor (continued). "We also suggest to include Batf2 as therapeutic target against cancer as Batf2 has been shown as a novel tumor suppresser gene, inhibiting growth of cancer cells through repression of hepatocyte growth factor receptor / MET signaling." (PMID 26376615, 2015). "Moreover, we also found that GBM tumor type affected survival with regard to BATF2 expression, with classical and proneural forms demonstrating the greatest increase in survival." (PMID 40945729, 2025). "In addition, survival outcomes differed by GBM tumor subtype, with minimal effects observed in mesenchymal and neural forms, indicating that additional genetic variations present across subtypes of GBM impact the efficacy of BATF2 as a tumor suppressor." (PMID 40945729, 2025). "Previous studies have demonstrated that BATF2 inhibited the phosphorylation of AKT by PI3K/AKT pathway, then suppressed cell migration capacity and enhanced the immune response to tumor cells 30, 31, suggesting that BATF2 played a significant regulatory role in the AKT signaling." (PMID 39629124, 2024). "BATF2 belongs to the activator protein 1 (AP-1) family and inhibits AP-1 activity mainly through interacting with AP-1 via its bZIP domain, thereby leading to tumor repression." (PMID 38420020, 2024). "Dysregulation of BATF2 is observed in different tumors, which can contribute to tumor progression." (PMID 37777155, 2023). "Interestingly, AMD3100 treatment drastically reduced tumour growth in BATF2 knock-down U87-MG cells (U87-sh-554 and U87-sh-1068)." (PMID 33452462, 2021). "In our study, we found that BATF2 effectively inhibited tumour growth." (PMID 33452462, 2021). "Pieces of evidence show that the BATF-2 gene, though expressed in a variety of normal tissue cells (e.g., melanocytes, astrocytes, pancreatic mesothelial cells, and prostate epithelial cells), can selectively inhibit the growth of tumor cells." (PMID 34565331, 2021). "Thus, we counted the number of BATF2+ EVs in plasma bone marrow of U251-BATF2 tumour-bearing mice by using the Exo-counter platform." (PMID 33452462, 2021). "Furthermore, subcutaneous injection of U251-Ctrl and U251-BATF2 cells demonstrated that upregulation of BATF2 significantly reduced tumour volume and weight by ~64.8% (p < 0.01)." (PMID 33452462, 2021). "BATF2 is a nuclear transcription factor that contacts AP-1 to exert tumour-suppressive effects." (PMID 33452462, 2021). "As expected, downregulation of BATF2 in U87-MG cells promoted tumour growth." (PMID 33452462, 2021). "BATF2, also known as SARI, has been implicated in tumor progression." (PMID 32650804, 2020). "In summary, our current findings reveal a tumor suppressor role of BATF2 in GC development." (PMID 32650804, 2020). "The expression of the BATF2 gene, which is located on human chromosome 11q (mouse chromosome 19), is reduced in various types of cancer, acting as a tumor suppressor and prompting apoptosis in tumor cells." (PMID 32166887, 2020). "A previous study showed that type I IFNs induced the expression of Batf2 in tumor cells." (PMID 30753547, 2019). "Furthermore, our ELISA data indicated that the increased VEGFA, MMP2, and MMP-9 levels upon BATF2 downregulation were significantly impaired after AMD3100 injection, suggesting that these tumour-promoting cytokines associated with MDSCs were also blocked by AMD3100." (PMID 33452462, 2021). "Thus, we speculate that the tumor-suppressor BATF2 molecules are released from exosomes to the outside of the cell to support tumor cell proliferation and tumor growth." (PMID 34778372, 2021). "Thus, we confirmed that BATF2 acts as a tumor suppressor in GC." (PMID 32650804, 2020). "The loss of SARI (suppressor of AP-1 or BATF2) in all tumour cases also did not suppress E-Cad." (PMID 29976164, 2018). "In breast cancer research, it has been shown that targeting BATF2 suppresses CCN1 transcriptional activity, thereby reducing tumor cell proliferation and invasion." (PMID 39629124, 2024).
tumor (continued). "In these cells, forming 3D tumor spheres, we observed elevated markers of stem cell-like traits and an increase in p-AKT and its target genes in the BATF2-knockdown (shBATF2) group, suggesting a link with AKT signaling." (PMID 39629124, 2024). "We extended to evaluate BATF2's impact on spheroid and tumor formation, employing dilution assays with AGS and MKN-45, which were confirmed as BATF2 low expression cell line, to assess the influence of BATF2 overexpression both in vitro and in vivo." (PMID 39629124, 2024). "Our results confirmed that ETV7 and/or BATF2 knockdown elevates the PAI-1/ERK pathway, increasing BC cell tumor-promoting behaviors." (PMID 38282047, 2024). "Therefore, future drugs targeting the NES region of specific tumour suppressors, such as BATF2, characterised by abnormal cytoplasmic localisation and selective tumour‐suppressing capacity, may provide higher efficacy and safety for the precise treatment of CRC." (PMID 37151195, 2023). "A significant enrichment of the BATF2 gene was found in patients who went on to have a complete response to CRT, which is consistent with findings that BATF2 depletion in tumour compared with normal tissue is correlated with poor prognosis in CRC36." (PMID 37161675, 2023). "BATF-2, also known as suppressor of activator protein-1 regulated by interferon (SARI), is a recently discovered tumor suppressor gene using subtractive hybridization in 2008." (PMID 34565331, 2021). "In our study, low BATF2 expression in NPC tissues indicates its tumor suppressor roles in NPC, which is further evidenced by prolonged overall survival of BATF2-positive patients." (PMID 34778372, 2021). "We used the TIMER database to analyze the differential expressions of CD38, ACE2, BATF2, HLA-DOB, and WARS between various tumor tissues and normal tissues." (PMID 34868310, 2021). "The transcription factor BATF2, which belongs to the BATF family, was initially characterized as an inhibitor of tumor growth through the suppression of AP-1 activity." (PMID 30753547, 2019). "An in vivo tumor xenograft model further verified that BATF2 overexpression combined with 5-Fu treatment led to a 67.4% reduction in tumor growth, without affecting body weight, compared to a minimal effect in control cells with overexpression of BATF2." (PMID 39629124, 2024). "BATF2 is mainly expressed in normal cells but not in the corresponding tumor cells, while the restoration of BATF2 inhibits cancer cell proliferation, invasion and metastasis, highlighting its potential as a therapeutic target in cancer." (PMID 38420020, 2024). "We next examined the association between the three model genes (CD36, BATF2 and MYB) and immunotherapy response using datasets composed of pre-treated tumor biopsies from responders and non-responders in the TIGER database." (PMID 37781029, 2023). "Although there are no specific BATF2 inducers at present, our previous studies demonstrated that dexamethasone (Dex), a first‐line drug in many tumours, was capable of inducing BATF2 expression." (PMID 37151195, 2023). "BATF2 downregulated the expressions of hypoxia-inducible factor (HIF-1a) and vascular endothelial growth factor via targeting ceruloplasmin, thus inhibiting angiogenesis and tumor growth." (PMID 34778372, 2021). "To demonstrate whether BATF2-EVs have inhibitory effects on SDF-1α, we subcutaneously injected U251-Ctrl and U251-BATF2 supernatant-derived EVs per 3 d after 7 d of U251 tumour establishment." (PMID 33452462, 2021). "We observed that BATF2 inhibit both HIF-1α and SDF-1α expression in U251 cells and tumour tissues." (PMID 33452462, 2021). "The in vivo experiments showed that a lower number of BATF2-overexpressing tumor cells failed to initiate tumor formation compared to control cells, suggesting a diminished stem-like potential in cells with elevated BATF2 levels." (PMID 39629124, 2024).
tumor (continued). "It has been reported that BATF2 is primarily expressed in normal cells but not in the corresponding tumor cells, while the upregulation of BATF2 has been shown to inhibit cancer cell proliferation, angiogenesis, invasion and metastasis, underscoring its importance in cancer therapy." (PMID 38420020, 2024). "To our surprise, knocking down BATF2 did not reduce tumor burden in our model indicating that the tumor control efficacy we observed in patients may be due to host since nude mice is immune compromised." (PMID 37777155, 2023). "However, overexpression of BATF2 did not affect tumour cell proliferation and migration, but leading to decreased MDSCs infiltration in tumour tissues." (PMID 33452462, 2021). "In addition, immunohistochemical (IHC) staining for proliferating cell nuclear antigen (PCNA) in subcutaneous tumour tissues indicated that upregulated BATF2 expression did not inhibit tumour cell proliferation." (PMID 33452462, 2021). "Furthermore, BATF2 did not affect invasion and migration by tumour cells, as shown by transwell migration assay in vitro." (PMID 33452462, 2021). "A sharp contrast in BATF2 staining was observed between the tumor and nontumor tissues." (PMID 32650804, 2020). "The IHC microarray showed that 63/129 (48.83%) cases were BATF2-positive, with BATF2 predominately expressed in the nucleus of NPC cells and elevated BATF2 expression scores in stage I-II NPC patients and those without recurrent tumor or metastasis in the cervical lymph nodes." (PMID 34778372, 2021).